IL1B (interleukin 1 beta)
Diseases named in the same sentence as IL1B in open-access papers (continued):
Sharing a sentence is not in itself a finding about the gene and the disease.
osteoarthritis (continued). "Studies have shown that P. lobata polysaccharides can reduce joint swelling symptoms, decrease the production of serum inflammatory cytokines TNF-α, IL-1β, and IL-6, and slow down inflammation in osteoarthritis (OA) in rats." (PMID 39795251, 2025). "For example, reduced levels of 3′-tRFs derived from tRNA-Cys and tRNA-Thr were detected in chondrocytes in IL-1β-induced osteoarthritis and in pancreatic acinar cells in a model of acute pancreatitis." (PMID 40723836, 2025). "Research has found that IL-1β is a key factor in inducing osteoarthritis, capable of exacerbating cellular inflammatory damage, inducing apoptosis, and ultimately leading to the destruction of articular cartilage." (PMID 40520186, 2025). "Studies have found that BA inhibits IL-1β-induced inflammation by activating PPAR-γ in human osteoarthritis chondrocytes." (PMID 40647158, 2025). "Ginsenoside CK was demonstrated to exert cartilage-protective effects in chondrocytes from osteoarthritis patients through the regulation of IL-1β-induced MAPK pathways." (PMID 40507179, 2025). "IL-1β plays a pivotal role in the development of osteoarthritis, capable of triggering inflammatory reactions alone or in conjunction with other mediators, affecting the joint’s articular cartilage and other structural components." (PMID 40343288, 2025). "Studies have shown that blood derivatives such as ACS can reduce the pain and damage of osteoarthritis by reducing IL-1β and improve wound healing by reducing inflammation." (PMID 40896180, 2025). "We assessed the impact of TRPV3 downregulation on inflammatory mediators, including iNOS and COX-2, in IL-1β-stimulated chondrocytes, as their dysregulation contributes to the pathobiology of osteoarthritis." (PMID 40166423, 2025). "Chlorogenic acid reversed the reduction in collagen II and the increase in iNOS/NO, IL-6, MMP-13, and COX-2/PGE2 levels in IL-1β-induced human SW-1353 chondrocytes, an in vitro model of osteoarthritis." (PMID 41515347, 2025). "We previously demonstrated its anti-osteoarthritic effects in IL-1β-stimulated human chondrocytes and in a rat model of monosodium iodoacetate–induced osteoarthritis, showing significant reductions in cartilage degradation and inflammatory markers." (PMID 41155257, 2025). "Macrophages were stimulated with IL1β to mimic osteoarthritis-related inflammatory responses in vitro and then treated with curcumin or nanoemulsion." (PMID 41303695, 2025). "An IL-1β-induced osteoarthritis chondrocyte model was created to study the therapeutic effects of FoxO3-NETT@SMs on osteoarthritis chondrocytes." (PMID 40041910, 2025). "This includes sleep apnea, type 2 diabetes, coronary heart disease, respiratory system disorders, and pain syndromes, like osteoarthritis that is exacerbated nocturnally by TNFα, IL-1β, and other somnogenic immunological modulators." (PMID 40137093, 2025). "Administration of miR‐144‐3p mimics to an anterior cruciate ligament transection rat model helped alleviate the progression of osteoarthritis and reduce the quantity of IL‐1β‐positive cells in the synovial tissue." (PMID 40067024, 2025). "ACS contains different type of cytokines, such as interleukin (IL)-1β, IL-6, IL-1 receptor antagonist (IL-1Ra), and IL-10, used mainly in osteoarthrosis." (PMID 40896180, 2025). "PBMT improved OARSI scoring of osteoarthritis and suppressed IL-1β, caspase-3, and MMP-13 expression." (PMID 41009563, 2025). "In a mouse model of traumatic osteoarthritis, both curcumin and curcumin-encapsulated nanoparticles inhibited the mRNA expression of pro-inflammatory factors such as IL-1β and TNF-α." (PMID 40431555, 2025). "IL-1b is widely used in osteoarthritis research to establish in vitro models that mimic the inflammatory environment by inducing chondrocyte catabolic activity and inflammation." (PMID 41154575, 2025). "IL-1β plays a crucial role in osteoarthritis and fracture healing by modulating chondrocyte behavior and cartilage degradation." (PMID 39851510, 2025).
osteoarthritis (continued). "Due to inflammation, NO production increased through the NF-κB signaling pathway, which regulates three pro-inflammatory cytokines of osteoarthritis, including IL-1β, IL-6 and TNF-α." (PMID 39204123, 2024). "Several studies have reported a significant increase in the expression of IL-1β in the serum and synovial fluid of osteoarthritis patients." (PMID 38741587, 2024). "This is in line with other studies, which show a decline in the levels of IL-1β and TNFα in the late stages of osteoarthritis compared to earlier stages of the disease." (PMID 38200556, 2024). "IL-1 blockers such as canakinumab (anti-IL-1β antibody) and anakinra (recombinant IL-1R antagonist) are effective against various autoinflammatory diseases including scleritis, Kawasaki disease, osteoarthritis, rheumatoid arthritis, and psoriasis." (PMID 38704587, 2024). "Interleukin-1β (IL-1β) is one of several inflammatory factors that can lead to the occurrence of osteoarthritis by inducing the overexpression of related metabolic enzymes and inflammatory cytokines, such as NO, PGE2, ADAMTS, and MMPs." (PMID 38741587, 2024). "Here, we investigated Cx43 modulation mediated by inflammatory stimuli involved in osteoarthritis, i.e., 10 ng/mL Tumor Necrosis Factor alpha (TNFα) and/or 1 ng/mL Interleukin-1 beta (IL-1β), in primary chondrocytes (CH) and osteoblasts (OB)." (PMID 39126115, 2024). "The dose-dependent increase of cGAS expression and cellular senescence induced by IL-1β was also evidenced in chondrocytes and the osteoarthritis development in mice." (PMID 39034400, 2024). "Previous studies indicate that interleukin-1 beta (IL-1β) and tumour necrosis factor alpha (TNFα) are instrumental in the progression of osteoarthritis." (PMID 38200556, 2024). "This study investigated the function of GPA on osteoarthritis (OA) in IL‐1β‐stimulated mouse chondrocytes and mouse OA model." (PMID 38520209, 2024). "Earlier studies have shown elevated levels of GM-CSF and IL-1β in synovial fluid and synovial membrane in RA compared to other types of inflammatory arthritis or osteoarthritis." (PMID 39394168, 2024). "The accumulation of β-catenin and Wnt5a in IL-1β-induced osteoarthritis chondrocytes elevated the expression of downstream transcription factors, such as RUNX2." (PMID 38312628, 2024). "By targeting the DAZAP1 and MAPK pathways, upregulated miR-320a improved IL-1β-induced osteoarthritis by enhancing chondrocyte proliferation, reducing apoptosis, and decreasing inflammatory response." (PMID 38816719, 2024). "The development of osteoarthritis is significantly influenced by IL-1β, a pro-inflammatory cytokine that assumes a critical role." (PMID 38869746, 2024). "The IL-1β is a potential trigger of osteoarthritis whose levels were elevated in the synovial fluid of the patients and mice models of OA." (PMID 38519981, 2024). "A preceding study found that FJH-UBS suppressed inflammatory response and cartilage degradation by inhibiting the activity of the MAPK and NF-κB signaling systems in an osteoarthritis cell model induced by treating SW1353 cells with IL-1β." (PMID 38542192, 2024). "Inflammation models with the proinflammatory cytokine interleukin-1β (IL-1β) are widely used in the in vitro investigation of new therapeutic approaches for osteoarthritis (OA)." (PMID 39791731, 2024). "In chondrocytes from mice with IL-1β-induced osteoarthritis, decreased protein expression of GPX4 and SLC7A11 and lipid ROS accumulation were observed, which inhibited the expression of type II collagen in chondrocytes and affected bone and joint health." (PMID 38678018, 2024). "An independent clinical trial of LC supplementation in patients with osteoarthritis showed that LC significantly reduced serum levels of IL-1b and MMP-1." (PMID 38674921, 2024). "In this study, chondrocytes were induced with IL-1β to mimic osteoarthritis in vitro and treated with different doses of puerarin and celecoxib." (PMID 37548663, 2024).
osteoarthritis (continued). "Among the osteoarthritis test groups, only the O + M group exhibited a notable reduction in IL-1β mRNA expression relative to the OC group." (PMID 38542192, 2024). "Three main pro-inflammatory cytokines that engage in the pathophysiology of osteoarthritis are IL-1β, IL-6, and TNF-α." (PMID 39204123, 2024). "They induced an osteoarthritis (OA) model in vitro using IL-1β and observed a substantial reduction in the proliferation and migration of chondrocytes." (PMID 38312628, 2024). "IL-1β stimulation also drives the increase in catabolic factors that has already been described for their role in cartilage breakdown in osteoarthritis." (PMID 38543230, 2024). "The production of two inflammatory cytokines, IL-18 and IL-1β, is correlated with the presence of uric acid in the synovial fluid; among these, IL-18 was found to correlate with osteoarthritis progression." (PMID 38548957, 2024). "Previous research has indicated that miR-27a can enhance autophagy and apoptosis in IL-1β-treated articular chondrocytes in osteoarthritis." (PMID 39413115, 2024). "Patients with osteoarthritis exhibit higher levels of inflammatory cytokines IL-1β, IL-6, and TNF-α in the blood, synovial fluid, and cartilage tissue compared to healthy individuals." (PMID 38542192, 2024). "The inflammation in osteoarthritis is regulated by biochemical substances, such as prostanoids, cytokines (IL-1α, IL-1β, TNF-α, PGE2), proteases, and ROS produced by synoviocytes and chondrocytes." (PMID 39204123, 2024). "THP-1 cells underwent treatment with β-amyrin, stigmasterol, and the YTPS formulary extract, and individual herbal extracts were evaluated with pivotal cytokines contributing to the progression of osteoarthritis, IL-1β, IL-6, and TNF-α." (PMID 39204123, 2024). "In chondrocytes from humans with osteoarthritis, IL-1β not only inhibited chondrocyte proliferation but also induced apoptosis." (PMID 38678018, 2024). "As a member of the IL-1 family, IL-1β was demonstrated to be a key player in the pathogenesis of several conditions, including osteoarthritis." (PMID 38784540, 2024). "They reported that inhibition of autophagy enhances IL-1β-induced changes in osteoarthritis-related genes, while activation of autophagy can inhibit the occurrence of osteoarthritis by removing ROS from damaged mitochondria." (PMID 39440032, 2024). "The role of IL-1β activated apoptosis signaling pathways plays a central role in the development and progression of osteoarthritis." (PMID 39791731, 2024). "Verbascoside at 20 mg/kg doses prevented the development of osteoarthritis in rats by lowering proinflammatory interleukin (IL-1β, IL-6) and tumor necrosis factor (TNF)-α." (PMID 38790677, 2024). "To mimic the pathogenesis of osteoarthritis in the joint space of humans for our in vitro OA model, we stimulated human primary articular chondrocytes with IL-1β." (PMID 38538870, 2024). "Previous studies have examined synovial fluid of patients with osteoarthritis and found elevated IL-1β and complement proteins which match our in vitro studies." (PMID 38538870, 2024). "After defining the articular part of the in vitro osteoarthritis model, a cocktail of human recombinant TNFα and IL-1β at low concentration was administered to cells as these 2 pro-inflammatory cytokines are present in joints suffering from OA." (PMID 36271312, 2023). "One study found that Danshensu inhibits IL-1β-induced inflammatory response in chondrocytes and osteoarthritis by inhibiting NF-κB signaling pathway." (PMID 37221510, 2023). "Overexpression of lncRNA H19 enhanced apoptosis and decreased the proliferation in IL-1β-mediated chondrocytes via sponging miR-106a-5p in osteoarthritis." (PMID 37779916, 2023). "In IL‐1β‐induced osteoarthritis, we found that the level of ROS was increased while the activities of antioxidant enzymes were decreased." (PMID 37249294, 2023).
osteoarthritis (continued). "On the other hand, it has been shown that CD44 plays a role in stimulating TLR2 downstream targets with a subsequent progression of osteoarthritis as evidenced by the upregulation of NFκB-, IL-1B- as well as TNFA gene expression in human macrophages." (PMID 37234812, 2023). "In OA patients, higher levels of pyroptosis-associated inflammatory vesicles and increased levels of the inflammatory factors IL-1β and IL-18 have been detected in the joint fluids, which can increase chondrocyte pyroptosis and inflammation in osteoarthritis." (PMID 38264652, 2023). "In vivo, the obese mice fed high-fat diets presented with osteoarthritis-like changes and increased the expression of Interleukin-1 Beta (IL-1B), Matrix metalloproteinase-3 (MMP-3) and leptin in temporomandibular joints." (PMID 37464321, 2023). "Salvianolic acid B reduced IL-1β-mediated inflammatory cytokine production in chondrocytes in osteoarthritis and protected osteoarthritis progression." (PMID 37779916, 2023). "Correlation of leptin and interleukin-1 beta (IL-1β) levels with clinical parameters of metabolic syndrome and osteoarthritis." (PMID 37703108, 2023). "In particular, lower expression of FBXW7 and higher expression of VEGF and HIF-1α were observed in osteoarthritis cartilage and IL-1β-mediated degenerated chondrocytes." (PMID 37359559, 2023). "Lf was found to prevent the programmed cell death of chondrocytes induced by interleukin-1 beta (IL-1β), a cytokine known to contribute to osteoarthritis (OA) development." (PMID 37680888, 2023). "In osteoarthritis, NF-κB is frequently activated, often in response to factors like cytokines, including IL-1β and TNF-α, which stimulate the release of MMPs and other catabolic enzymes, thereby exacerbating osteoarthritis." (PMID 38132929, 2023). "And to our knowledge, the relationship between OA and TFRC was not reported before; so we firstly identified that TFRC was upregulated in IL-1β-stimulating chondrocytes, simulating the pathophysiological state of patients with osteoarthritis." (PMID 36950524, 2023). "The expression of this protein was associated with levels of inflammatory cytokines (IL-1β and TNF-α) in osteoarthritis." (PMID 37936684, 2023). "Stachydrine has been shown to have anti-inflammatory properties in primary human chondrocytes isolated from subjects with osteoarthritis that were treated with IL-1β." (PMID 37512580, 2023). "Cartilage plugs exposed to this cocktail of TNFα and IL-1β were therefore considered as a simplified in vitro model of osteoarthritis." (PMID 36271312, 2023). "Leptin and interleukin-1 beta (IL-1β) levels among different groups categorized by age, body mass index (BMI), number of involved joints, and disease duration in osteoarthritis patients." (PMID 37703108, 2023). "Sesamin, a lipid-soluble lignan, can inhibit IL-1β signalling in chondrocytes to achieve its anti-inflammatory effect and inhibit the degradation of collagen II and proteoglycans, which can treat osteoarthritis." (PMID 37525208, 2023). "SIRT3 can also ameliorate osteoarthritis by regulating chondrocyte autophagy by inhibiting the IL-1β-induced PI3K/Akt/mTOR signaling pathway." (PMID 37196115, 2023). "This compound suppressed the expression of inducible NO synthase (iNOS) and cyclooxygenase-2 (COX-2), as well as the IL-1β-induced inflammatory response in osteoarthritis by suppressing the NF-κB signaling pathway." (PMID 37373385, 2023). "To establish osteoarthritic (OA) conditions, we selected the cytokines IL-1β and IL-17 for use in this study due to their critical role in the onset and progression of osteoarthritis." (PMID 37762639, 2023). "As an inflammatory factor, IL-1β plays an extremely important role in the development of osteoarthritis." (PMID 36982438, 2023).
osteoarthritis (continued). "Salvianolic acid inhibited the release of inflammatory cytokines from IL-1β-induced OA chondrocytes and had a protective effect against osteoarthritis through inhibiting the activation of NF-κB and p38/MAPK pathways to exert anti-inflammatory effects in OA." (PMID 37507774, 2023). "LncRNA SNHG1 (small nucleolar RNA host gene 1) has been reported to repress miR-16-5p-mediated p38 MAPK and NF-κB pathways, such as p-p65, ERK1/2 and p-p38, leading to attenuation of IL-1β-mediated osteoarthritis." (PMID 37779916, 2023). "Aqueous extract of Codium fragile alleviates IL-1β-induced osteoarthritis in rat primary chondrocytes and rat osteoarthritis models via MAPK/NF-κB pathway." (PMID 37221510, 2023). "Interleukin-1β (IL-1β) is an inflammatory cytokine that is recognized to be highly differentially expressed in osteoarthritis compared to normal chondrocytes." (PMID 36950524, 2023). "Piperine has an anti-inflammatory effect and can inhibit the expression levels of inflammatory factors (iNOS, COX-2) and degenerative factors (MMP3, MMP13) in IL-1β-stimulated osteoarthritic chondrocytes, thereby treating osteoarthritis." (PMID 37525208, 2023). "Osteoarthritis is mentioned as an inflammatory process associated with active secretion of TNF-α and IL-1β." (PMID 37443993, 2023). "One study showed that protectin DX repressed IL-1β-involved inflammation and ameliorated osteoarthritis development via regulation of the AMPK and NF-κB pathways in chondrocytes." (PMID 37779916, 2023). "The level of pyroptosis-associated inflammasomes is high in the articular fluid of patients with OA and can increase the levels of IL-1β and IL-18, both of which can increase cartilage cell pyroptosis and inflammatory responses in osteoarthritis." (PMID 36982438, 2023). "circCDK14 ameliorated IL-1β-induced osteoarthritis chondrocyte injury through the miR-1183/KLF5 pathway." (PMID 36804426, 2023). "In a recent study, the aqueous extract of Codium fragile ameliorated osteoarthritis by regulating the MAPK/NF-κB pathway in IL-1β-induced osteoarthritis rats." (PMID 37629080, 2023). "Our observation of the anti-IL-1β activity of TA in human osteoarthritis chondrocytes prompted us to further test the anti-osteoarthritis therapeutic effect in the MIA-induced OA rat model." (PMID 37079558, 2023). "On a molecular level, earlier studies performed in animal models of osteoarthritis have shown that HMW HA inhibits IL-1β expression in synoviocytes." (PMID 37107200, 2023). "Altogether, these results indicate that plugs of cartilage cultured with 1 ng/mL TNFα and 0.1 ng/mL IL-1β develop a “OA-like” phenotype and constitute a good and representative osteoarthritis in vitro model for this pathology." (PMID 36271312, 2023). "With the progress of the experiment, IL‐1β gradually increased and was significantly correlated to the progression of osteoarthritis in the experimental and control groups of rats." (PMID 35894841, 2022). "For several polymorphisms in the IL1B locus, in the IL1RN VNTR and also RANK, KREMEN2 among others associations with osteoarthritis were described." (PMID 36518750, 2022). "Inflammation and oxidative stress are the main factors involved in osteoarthritis and aging, respectively, with the production of several pro-inflammatory cytokines such as Interleukin 1β (IL1β) and reactive oxygen species." (PMID 36498698, 2022). "Although IL-1β was used in the induction of inflammation in the osteoarthritis study, that cytokine can bind to the same receptor as IL-1α and thereby can be thought to evoke similar inflammatory conditions." (PMID 35661979, 2022). "ELISA results demonstrated that exogenous α2MRS significantly inhibited the induction of MMP-13 (p = 0.001), TNF-α (p = 0.005), and IL-6 (p < 0.001) activity in IL-1β-induced human primary osteoarthritis chondrocytes." (PMID 36133821, 2022). "Inflammation is one of the key feature of OP, and Il-1b can induce experimental osteoarthritis in chondrocytes." (PMID 35329547, 2022).